THSD7A (thrombospondin type 1 domain containing 7A)
Diseases named in the same sentence as THSD7A in open-access papers (continued):
Sharing a sentence is not in itself a finding about the gene and the disease.
idiopathic membranous nephropathy (16 papers, 2015 to 2024). "High levels of PLA2R and THSD7A expression have been observed in the kidneys of patients with idiopathic membranous nephropathy (IMN) and are associated with a poor prognosis." (PMID 39911669, 2024). "The understanding of idiopathic membranous nephropathy was limited until the discovery of thrombospondin type-1 domain containing 7A or THSD7A and phospholipase A2 receptor (PLA2R), the protein involved in this patient." (PMID 39759600, 2024). "Thrombospondin type 1 domain-containing 7A (THSD7A) is a recently identified target antigen of idiopathic membranous nephropathy (iMN)." (PMID 30868298, 2019). "Thrombospondin type-1 domain-containing 7A (THSD7A) is a target antigen in idiopathic membranous nephropathy (MN)." (PMID 30727973, 2019). "A second antibody specific for the autoantigen thrombospondin type 1 domain–containing 7A (THSD7A) has been detected in up to 5% of patients with idiopathic membranous GN, typically in those who were seronegative for the PLA2R autoantibody (<15% cases)." (PMID 31475005, 2019). "(ii) Assessment of glomeral expression of PLA2R1 and of THSD7A antigen in case of PLA2R1 seronegative MN deposits is at present mandatory in idiopathic membranous nephropathy." (PMID 29511687, 2018). "(i) The prevalence of anti-PLA2R1 and anti-THSD7A antibodies is approximately 70% and 2% in adults with idiopathic membranous nephropathy." (PMID 29511687, 2018). "Characteristics of idiopathic membranous nephropathy (MN) patients with enhanced granular expression of thrombospondin type-1 domain-containing 7A (THSD7A) or M-type phospholipase A2 receptor (PLA2R) in the glomeruli." (PMID 26393352, 2015). "Currently, several specific antigens, M-type receptor for secretory phospholipase A2(PLA2R1), thrombospondin type-1 domain-containing 7A(THSD7A), and neural epidermal growth factor-like 1 protein (NELL-1), are discovered associated with the onset of idiopathic membranous nephropathy (IMN)." (PMID 34703677, 2021). "Prevalence of enhanced granular expression of thrombospondin type-1 domain-containing 7A (THSD7A) and M-type phospholipase A2 receptor (PLA2R) in the glomeruli of patients with idiopathic membranous nephropathy (MN) and secondary MN." (PMID 26393352, 2015). "We present a case of idiopathic membranous nephropathy with anti-PLA2R negative and THSD7A positive with an underlying metastatic neuroendocrine carcinoma." (PMID 36968937, 2023). "Nevertheless, up to 20% of patients with idiopathic membranous GN do not have detectable autoantibodies to PLA2R or THSD7A, suggesting the possibility that unidentified autoantibodies targeting other auto-antigens may be contributing." (PMID 31475005, 2019). "In idiopathic membranous nephropathy (IMN) the immune complexes are formed by circulating antibodies binding mainly to one of two naturally-expressed podocyte antigens: the M-type receptor for secretory phospholipase A2 (PLA2R1) and the Thrombospondin type-1 domain-containing 7A (THSD7A)." (PMID 31447839, 2019).
nephrotic syndrome (8 papers, 2020 to 2025). A collection of symptoms that include severe edema, proteinuria, and hypoalbuminemia; it is indicative of renal dysfunction. "Together, these results show the development of a nephrotic syndrome in wild-type BALB/c mice upon immunization with THSD7A." (PMID 36709213, 2023). "When calculating a combined nephrotic syndrome clinical score, which involves the parameters proteinuria, hypoalbuminemia, hyperlipidemia, and weight gain, THSD7A-immunized animals had significantly higher values than controls." (PMID 36709213, 2023). "MN can be diagnosed in patients presenting with nephrotic syndrome and positive levels of PLA2R and THSD7A in the serum, but renal biopsy is uniquely informative in patients who are often PLA2R-negative and do not have typical nephrotic syndrome." (PMID 40659521, 2025). "Following a relapse of nephrotic syndrome in May 2021 (ACR 5 g/g, serum albumin concentration of 22 g/L, serum creatinine level of 168 μmol/L, anti-PLA2R at 249 IU/mL, and anti-THSD7A negative), anti-rituximab antibodies were monitored and found to be negative." (PMID 38540991, 2024). "In addition, some studies showed that the serum anti-PLA2R antibody, anti-THSD7A antibody, anti-SOD2 antibody, and anti-ENO antibody were all negative in IMN patients with a low proportion of nephrotic syndrome at onset, high plasma albumin level, and high disease remission rate." (PMID 32117644, 2020).
prostate carcinoma (8 papers, 2009 to 2024). A carcinoma that arises from epithelial cells of the prostate gland. "In a previous study, we were able to show that the expression of THSD7A shows an association with unfavorable prognostic parameters in prostate cancer." (PMID 39000462, 2024). "To our knowledge we are the first to show that THSD7A positivity is associated with high FAK expression in prostate cancer." (PMID 36673031, 2023). "Among other findings, we demonstrated that THSD7A overexpression is significantly associated with unfavorable prognostic parameters in prostate cancer, including the tumor stage, Gleason grade and lymph node metastasis as well as PSA recurrence." (PMID 36673031, 2023). "THSD7A expression is significantly associated with unfavorable prognostic parameters in prostate cancer." (PMID 36673031, 2023). "In former studies, we showed that THSD7A expression is associated with unfavorable prognostic parameters in prostate cancer and is linked to a high expression of focal adhesion kinase (FAK)." (PMID 37443605, 2023). "In a recent study, we could show that THSD7A positivity is associated with high FAK expression in prostate cancer." (PMID 37445817, 2023). "Among them, THSD7A is relatively commonly expressed in colorectal cancer, renal cancer, breast cancer and prostate cancer, and it was recently found that the transcription level and protein level of THSD7A were significantly increased in gastric cancer." (PMID 38686366, 2024). "Like our recently published data on prostate cancer, THSD7A positivity showed at least a tendency towards high FAK expression in female patients with LSCC." (PMID 37445817, 2023). "Related gene chip studies have shown that THSD7A is highly expressed in the malignant tissues of prostate cancer, renal cell carcinoma, colorectal cancer, and breast cancer." (PMID 36506585, 2022). "In a recent study, we could show that positivity of Thrombospondin Type-1 Domain-Containing 7A (THSD7A) is associated with a high expression of Focal Adhesion Kinase (FAK) and with adverse clinicopathological parameters in prostate cancer." (PMID 37445817, 2023). "Given the potential involvement of THSD7A in FAK-dependent signaling pathways, THSD7A should be discussed as a therapeutic target in prostate cancer." (PMID 36673031, 2023). "In the European cohort, a 29-year-old female patient was diagnosed with systemic lupus erythematosus had positive serum THSD7A antibody, and in the Boston cohort, a 77 years old male SMN patient had active prostate cancer at the time of the diagnosis of MN." (PMID 29623759, 2018).
glomerular diseases (6 papers, 2018 to 2025). "All these results suggest that this anti-THSD7A antibody-induced mouse model develops heavy proteinuria and glomerulopathy that share pathologic features with human MN." (PMID 39086386, 2024). "The specificity of anti-PLA2R and anti-THSD7A antibodies is very high in terms of comparing patients with MN and other glomerular diseases." (PMID 33828546, 2021). "However, this survey identified that nephrologists have limited access to testing and exposure to antigens other than PLA2R, THSD7A, NELL1, and EXT1/2 even amongst glomerular disease experts." (PMID 40500560, 2025).
lung carcinoma (6 papers, 2017 to 2024). "In a clinical study, positive THSD7A staining was found in both glomeruli and cancer cells of patients with lung cancer, and remission of MN symptoms was observed after surgical resection, confirming the association of THSD7A with lung cancer and MN23." (PMID 37658161, 2023). "Additionally, remission of MN was observed after surgical resection of lung cancer, supporting a mechanistic role for THSD7A in the association between cancer and MN." (PMID 36248963, 2022). "However, the investigators concentrated rather on the coincidence of lung cancer and THSD7A-positive MN than on the role of THSD7A as a potential tumor marker in lung cancer Data on the association between THSD7A expression and clinicopathological parameters in LSCC are missing so far." (PMID 37445817, 2023). "There are a few studies that deal with THSD7A and lung cancer." (PMID 37445817, 2023). "Additionally, THSD7A was detected in lung cancer tissue, which was also THSD7A-positive MN23." (PMID 37658161, 2023). "Ten patients had a cancer: 2 with a lung carcinoma had PLA2R-Ag in immune deposits, none had circulating PLA2R-Ab; 1 with a gastric carcinoma had circulating anti-THSD7A-Ab and THSD7A-Ag in immune deposits." (PMID 28257452, 2017).
breast carcinoma (4 papers, 2019 to 2025). "The positive expression of THSD7A was detected in colorectal and breast cancer sections, and THSD7A was expressed in the membrane and cytoplasm of tumor cells." (PMID 31443644, 2019). "Meanwhile, the results showed that THSD7A was strongly positive in colorectal cancer and moderately positive in breast cancer, indicating that the THSD7A-positivity was expressed in different type of cancers with different patterns." (PMID 31443644, 2019). "In this study, we investigated the histologic expression of THSD7A in colorectal or breast cancers, as well as the relationship between THSD7A expression and proteinuria in the patients with cancers." (PMID 31443644, 2019). "All 20 patients (100%) with breast cancer were THSD7A positive and most of them had moderate positive expression of THSD7A." (PMID 31443644, 2019). "The results showed that THSD7A was positively expressed in colorectal cancer and breast cancer tissues by IHC staining." (PMID 31443644, 2019). "The significance of this study was that we demonstrated there would be high prevalence of THSD7A positive in colorectal and breast cancer." (PMID 31443644, 2019). "In this study, we investigated the histologic expression of THSD7A in colorectal or breast cancers, as well as the relationship between THSD7A expression and proteinuria in these patients." (PMID 31443644, 2019). "Positive expression rates of THSD7A in the two types of tumor tissues were very high, 97.5% in colorectal cancer, and 100% in breast cancer." (PMID 31443644, 2019). "The positive rates of THSD7A were 97.5% in colorectal cancer and 100% in breast cancer respectively, so it’s hard to find a match-paired control group of neoplastic patients with negative expression of THSD7A." (PMID 31443644, 2019). "THSD7A was expressed in colorectal cancers and breast cancers with high prevalence and might play an important role in the development of proteinuria in patients with cancers." (PMID 31443644, 2019). "The positive rate of THSD7A expression was very high in human colorectal cancer or breast cancer." (PMID 31443644, 2019). "THSD7A is notable for its high expression frequency, whereas the role of AGMO in breast cancer remains insufficiently elucidated in the literature." (PMID 41300329, 2025).
colorectal cancer (4 papers, 2019 to 2024). A primary or metastatic malignant neoplasm that affects the colon or rectum. "In other studies, THSD7A is differentially expressed in different solid tumors, including lung, breast, kidney, and colorectal cancers, which are of value for the prognosis of the disease." (PMID 36248963, 2022). "Total 79 cases (97.5%) with colorectal cancer were THSD7A positive and most of them had strong positive expression of THSD7A." (PMID 31443644, 2019). "A-C is the three categories of THSD7A staining intensity in colorectal cancer tissues: A, 3+; B, 2+; C, 1+." (PMID 31443644, 2019). "However, while further confirmed by immunohistochemical staining in tumor tissue sections in the study, they found that the positive rate of THSD7A was 100% in high grade group and 91.7% in low grade group in colorectal cancer entities." (PMID 31443644, 2019).
asthma (3 papers, 2019 to 2023). "Similarly, the pathogenic association of THSD7A-associated MN with asthma (cases 10 to 12) remains unclear, although hypereosinophilic disorders other than Kimura’s disease have been reported in association with MN." (PMID 30868298, 2019).
Autoimmunity (3 papers, 2021 to 2025). The occurrence of an immune reaction against the organism's own cells or tissues. "These patients were carefully screened and followed up, and none was found to have a tumor, suggesting that EXT1/EXT2 and THSD7A may be associated with autoimmunity." (PMID 39927251, 2025). "Personalized treatment on the initial pathological causes leading to the autoimmunity to PLA2R or THSD7A is not yet feasible, as our understanding on the upstream and downstream events contributing to PLA2R- and THSD7A-associated MN remain limited." (PMID 33808418, 2021). "Studies have suggested that most MN patients produced an autoimmune response for either PLA2R or THSD7A, but not for two antigens, indicating that both antigens are primary target of specific autoimmunity and verifies that PLA2R-related MN and THSD7A-related MN are separate disease entities." (PMID 36176440, 2022).
eosinophilia (3 papers, 2020 to 2023). "In summary, we report a case of THSD7A-associated MN in an adult woman with eosinophilia diagnosed by serum antibody testing as well as THSD7A staining in a renal biopsy." (PMID 31705303, 2020). "In this case, THSD7A-associated MN is thought to have occurred coincidentally with eosinophilia, but it cannot be completely denied that eosinophilia caused THSD7A-associated MN." (PMID 31705303, 2020). "Here, we report a case of THSD7A-associated MN with comorbid eosinophilia." (PMID 31705303, 2020). "The causal relationship between THSD7A-related MN and eosinophilia was unclear." (PMID 31705303, 2020). "More interestingly, inspired by two cases of THSD7A-associated MN accompanied by angiolymphoid hyperplasia with eosinophilia (ALHE), the researchers assumed that vascular endothelial growth factor A (VEGF-A) up-regulated the expression of THSD7A in endothelial cells in vitro." (PMID 33042109, 2020). "However, a few cases of THSD7A-associated MN with eosinophilia have been reported, and further clarification on the relationship between THSD7A-related MN and eosinophilia is warranted." (PMID 31705303, 2020). "Based on these, the case was considered as THSD7A-associated MN with comorbid eosinophilia." (PMID 31705303, 2020). "Further investigation based on a nationwide disease registry is required to understand the relationship between THSD7A-related MN and eosinophilia." (PMID 31705303, 2020).
esophageal squamous cell carcinoma (3 papers, 2017 to 2023). Esophageal squamous cell carcinoma (ESCC) is a type of esophageal carcinoma (EC) that can affect any part of the esophagus, but is usually located in the upper or middle third. "Recently, scavenger receptor class A member 5 (SCARA5) was reported to be the downstream gene of THSD7A in esophageal squamous cell carcinoma." (PMID 37443605, 2023). "Thrombospondin type 1 domain-containing 7A (THSD7A) was reported to play a procancer role in esophageal squamous cell carcinoma (ESCC)." (PMID 35755171, 2022). "However, the involvement of Thsd7a remains elusive in human Esophageal Squamous Cell Carcinoma (ESCC)." (PMID 28947992, 2017).
gastric cancer (3 papers, 2017 to 2024). A primary or metastatic malignant neoplasm involving the stomach. "Univariate and multivariate Cox regression analyses indicated that THSD7A was an independent risk factor for gastric cancer." (PMID 37905960, 2023). "Our purpose was to determine the molecular mechanisms underlying the functioning of THSD7A and its prognostic value in gastric cancer." (PMID 37905960, 2023). "Cox analysis showed that THSD7A was an independent risk factor for patients with gastric cancer." (PMID 37905960, 2023). "The functional enrichment analysis revealed that THSD7A expression in gastric cancer may be associated with pathways such as inflammatory responses, angiogenesis, EMT, focal adhesion, and cell adhesion molecules." (PMID 37905960, 2023). "In conclusion, the findings of this study revealed that upregulation of THSD7A expression in endothelial cells is associated with the recruitment of tumor-associated immunosuppressive cell infiltration as well as poor prognoses in patients with gastric cancer." (PMID 37905960, 2023). "Analysis of the data from the UALCAN datasets (cohorts), GSE27342, GSE29272, GSE54129, and GSE65801, revealed that THSD7A is significantly increased in gastric cancer tissues compared with that in normal gastric tissues (P<0.05)." (PMID 37905960, 2023). "High THSD7A expression suppressed the sensitivity of patients with gastric cancer to drugs, such as 5-fluorouracil, bleomycin, and cisplatin, and upregulated immune checkpoints, such as HAVCR2, PDCD1LG2, TIGIT, and CTLA4." (PMID 37905960, 2023). "Considered together, these findings suggest that the contribution of THSD7A to the development of gastric cancer cell invasion and drug resistance is multi-dimensional." (PMID 37905960, 2023). "Regarding the grade and TNM stage of gastric cancer, THSD7A was most significantly upregulated in higher grades (grade 3; P<0.001) and higher stages (stage II, III, and IV; P<0.001)." (PMID 37905960, 2023). "Current analyses combined with previous immune infiltration analyses, indicate that THSD7A not only induces a poor immune microenvironment, but also enables immune escape in gastric cancer." (PMID 37905960, 2023). "Subsequently, cell trajectory analysis revealed that THSD7A (+) endothelial cells are mainly located at the end of the differentiation trajectory, and that THSD7A expression increased with the progression of gastric cancer infiltration." (PMID 37905960, 2023). "GEPIA online analysis showed that patients with gastric cancer and high THSD7A expression had shorter overall survival (OS; P<0.05) and disease-free survival (DFS; P<0.05), compared with those with low THSD7A expression." (PMID 37905960, 2023). "Multivariate Cox analysis indicated that THSD7A expression (HR = 1.570, 95% CI: 1.050-2.350, P < 0.028) and age (HR = 1.033, 95% CI: 1.014-1.053, P < 0.001) were independent prognostic factors for gastric cancer." (PMID 37905960, 2023). "We used bulk RNA sequencing to examine the differential expression of THSD7A in gastric cancer and normal gastric tissues and explored the relationship between THSD7A expression and clinicopathological characteristics." (PMID 37905960, 2023). "In order to determine the interactions between THSD7A (+) endothelial cells and other cell subpopulations in the gastric cancer microenvironment, the cell subpopulations from gastric cancer tissue were isolated and re-annotated." (PMID 37905960, 2023). "Increased activity of the IL2-STAT5 signaling pathway was seen in gastric cancer patients with elevated levels of THSD7A expression." (PMID 37905960, 2023).